ASNSD1 (asparagine synthetase domain containing 1)
Synonyms: NS3TP1; Nbla00058; FLJ20752
Tractability: PROTAC: ubiquitination databases record sites on it.
Gene: Protein-coding gene on chromosome 2 (189,661,385 to 189,670,831, forward strand). Ensembl gene ENSG00000138381.
Subcellular location (Human Protein Atlas): Cytosol
Gene Ontology:
Molecular function: protein binding
Genetic constraint (gnomAD): Loss-of-function variants: 37 observed, 51.82 expected, observed/expected ratio (o/e) 0.71, 90% interval 0.55 to 0.94. The upper end of that interval is the gene's LOEUF score, 0.94, which puts it in group 3 of 6, group 1 being the genes least tolerant of losing a copy. Missense variants: 714 observed, 798.6 expected, observed/expected ratio (o/e) 0.89, 90% interval 0.84 to 0.95. Synonymous variants: 257 observed, 278.02 expected, observed/expected ratio (o/e) 0.92, 90% interval 0.83 to 1.02.
Homologues: Orthologues: chimpanzee ASNSD1 (99% identical), macaque ASNSD1 (96% identical), pig ASNSD1 (81% identical), dog ASNSD1 (80% identical), guinea pig ASNSD1 (77% identical), mouse Asnsd1 (75% identical), rat Asnsd1 (73% identical), tropical clawed frog asnsd1 (55% identical), zebrafish asnsd1 (54% identical), Drosophila melanogaster CG17486 (31% identical), Caenorhabditis elegans M18.3 (26% identical). Paralogues in human: ASNS (16% identical).
Diseases named in the same sentence as ASNSD1 in open-access papers:
ASNSD1 is named in the same sentence as 3 diseases in open-access papers, as found by Europe PMC text mining. Sharing a sentence is not in itself a finding about the gene and the disease. The quoted sentences say what the papers report.
medulloblastoma (3 papers, 2024 to 2025). A malignant, invasive embryonal neoplasm arising from the cerebellum. "Another example is the micropeptide ASDURF, a subunit of the PAQosome chaperone complex, which is translated from the uORF of the ASNSD1 gene and is required for medulloblastoma cell proliferation independently of the function of the ASNSD1 protein." (PMID 40076602, 2025). "The ASNSD1-uORF protein, also known as ASDURF, derived from a uORF within the ASNSD1 gene was found to exhibit elevated expression in medulloblastoma." (PMID 39333489, 2024). "The non-canonical translation of the micropeptide ASNSD1-uORF has been shown to be necessary for childhood medulloblastoma cell survival through its interaction with the prefoldin-like chaperone complex, presenting an attractive target for medulloblastoma therapy." (PMID 39311199, 2024).
memory impairment (1 paper, 2021). "The HGS gene ASNSD1 is involved in asparagine biosynthesis and its expression is decreased in our patients with severe memory impairment." (PMID 33986407, 2021). "ASNSD1, a gene involved in biological processes related to memory, showed diminished expression in patients with severe memory impairment." (PMID 33986407, 2021).
ASNSD1 also shares sentences with these, for which no sentence is quoted: liver fibrosis (2 papers).